ARHGAP36 (Rho GTPase activating protein 36)
Description:
GTPase activator for the Rho-type GTPases by converting them to an inactive GDP-bound state.
Synonyms: FLJ30058
Tractability: Antibody: UniProt predicts a signal peptide or a membrane-spanning region; the Human Protein Atlas places it where antibodies can reach.
Gene: Protein-coding gene on chromosome X (131,058,346 to 131,089,885, forward strand). Ensembl gene ENSG00000147256.
Subcellular location (Human Protein Atlas): Nucleoplasm; Plasma membrane; Vesicles
Gene Ontology:
Molecular function: GTPase activator activity
Biological process: actin filament organization; signal transduction
Cellular component: actin cytoskeleton
Homologues: Orthologues: chimpanzee ARHGAP36 (95% identical), rabbit ARHGAP36 (93% identical), macaque ARHGAP36 (93% identical), dog ARHGAP36 (88% identical), guinea pig ARHGAP36 (84% identical), rat Arhgap36 (79% identical), mouse Arhgap36 (79% identical), zebrafish arhgap36 (31% identical), tropical clawed frog arhgap36 (28% identical), Drosophila melanogaster RhoGAP102A (23% identical), Caenorhabditis elegans rga-6 (23% identical). Paralogues in human: ARHGAP6 (35% identical).
Diseases named in the same sentence as ARHGAP36 in open-access papers:
ARHGAP36 is named in the same sentence as 16 diseases in open-access papers, as found by Europe PMC text mining. Sharing a sentence is not in itself a finding about the gene and the disease. The quoted sentences say what the papers report.
medulloblastoma (3 papers, 2016 to 2021). A malignant, invasive embryonal neoplasm arising from the cerebellum. "For example, PRAJA2 might underlie the association of ARHGAP36 with Hh pathway-independent medulloblastoma subtypes, neuroblastoma, and/or endocrine cancers." (PMID 33999959, 2021). "In addition, mutations in the Arhgap36 locus that result in N-terminally-truncated protein products can drive medulloblastoma formation in mice, while normal fetal cerebellum only expresses ARHGAP36 isoform 1, which contains the longest N-terminal domain of all ARHGAP36 splice variants." (PMID 33999959, 2021). "Arhgap36 transcription has also been found to correlate with SMO inhibitor resistance in Hh pathway-dependent murine medulloblastomas." (PMID 33999959, 2021). "Arhgap36 overexpression in murine cerebellar granule neuron precursors, the cells of origin for certain medulloblastoma subtypes, induces Hh ligand-independent Gli activation and proliferation." (PMID 33999959, 2021). "We show that PKA inhibition by ARHGAP36 promotes derepression of the Hedgehog signalling pathway, thereby providing a simple rationale for the upregulation of ARHGAP36 in medulloblastoma." (PMID 27713425, 2016). "ARHGAP36 has previously been shown to activate the Hedgehog (Hh) signalling pathway and is upregulated in a subset of medulloblastoma, suggesting an important role in tumourigenesis." (PMID 27713425, 2016). "Moreover, elevated ARHGAP36 expression has been observed in Hh pathway-independent subtypes of human medulloblastoma, neuroblastoma, and endocrine cancers." (PMID 33999959, 2021). "ARHGAP36 may promote tumor growth through multiple pathways, as Arhgap36 has been identified as an oncogenic driver of both Hh pathway-dependent and independent medulloblastomas in mice." (PMID 33999959, 2021). "Our experiments thereby provide a mechanism by which aberrant ARHGAP36 expression may promote medulloblastoma formation." (PMID 27713425, 2016). "Furthermore, ARHGAP36 is up-regulated in medulloblastoma where Shh pathway is aberrantly activated, suggesting that similar mechanisms may be applied to tumorigenesis." (PMID 31305241, 2019).
neuroblastoma (3 papers, 2016 to 2021). Neuroblastoma (NB) is the most common solid, extracranial childhood tumor. "ARHGAP36 is expressed in neuroblastoma cells and promotes aberrant activation of the Hedgehog pathway and inhibits Protein kinase A (PKA) signaling." (PMID 32891179, 2020). "It will be interesting to further explore the role of ARHGAP36 and PKA in neuroblastoma." (PMID 27713425, 2016).
sarcopenia (3 papers, 2022 to 2024). Progressive decline in muscle mass due to aging which results in decreased functional capacity of muscles. "In this research, six genetic biomarkers closely associated with sarcopenia, including ARHGAP36, FAM171A1, GPCPD1, MT1X, ZNF415, and RXRG, were identified by WGNCA and LASSO analysis, which were used to future diagnose and screen for sarcopenia." (PMID 36147639, 2022). "Compared to normal samples, the expression levels of both MT1X and ARHGAP36 were upregulated in sarcopenia samples, while GPCPD1, FAM171A1, ZNF415, and RXRG showed lower expression in sarcopenia samples." (PMID 36147639, 2022). "Additionally, in patients with sarcopenia, MT1X and ARHGAP36 were upregulated, whereas FAM171A1, GPCPD1, ZNF415 and RXRG, were downregulated, demonstrating high diagnostic accuracy for sarcopenia and potential as predictive markers for screening." (PMID 38337720, 2024). "Moreover, six hub genes with AUC exceeding 0.9, including ARHGAP36, FAM171A1, GPCPD1, MT1X, ZNF415, and RXRG, were confirmed as diagnostic biomarkers for sarcopenia." (PMID 36147639, 2022). "We found the AUC values of GPCPD1, MT1X, ARHGAP36, FAM171A1, ZNF415, and RXRG on the validation dataset were 0.928, 0.75, 0.978, 0.961, 0.811, and 0.906, indicating that the six biomarkers had high diagnostic accuracy for sarcopenia." (PMID 36147639, 2022). "Finally, six hub genes with AUC exceeding 0.9, including GPCPD1, MT1X, ARHGAP36, FAM171A1, ZNF415, and RXRG, were defined as diagnostic biomarkers of sarcopenia." (PMID 36147639, 2022).
behavioral disorders (1 paper, 2021). "Genes linked to congenital and behavioral disorders included dynein axonemal intermediate chain 1, Rho GTPase Activating Protein 36, ATPase Na+/K+ Transporting Subunit Alpha 3 and 5-Hydroxytryptamine Receptor 2C while genes related to fitness effects include genes such as Cysteine-Three-Histidine." (PMID 34209092, 2021).
neural tube defect (1 paper, 2021). A congenital defect characterized by failure of the neural tube to close completely; this results in the presence of openings in the brain or spinal cord. "Most recently, an ARHGAP36 L94F variant was identified by whole-exome sequencing of spina bifida patients as a potential contributor to this neural tube defect, which can be caused by dysregulated Hh pathway activation." (PMID 33999959, 2021).
tumor (2 papers, 2016 to 2021). "Dependent on the signalling context in which PKA functions, aberrant ARHGAP36 expression could have both tumour suppressive and oncogenic roles." (PMID 27713425, 2016).
ARHGAP36 also shares sentences with these, for which no sentence is quoted: arterial hypertension (1 paper); Bazex-Dupre-Christol syndrome (1); cancer (1); emphysema (1); endocrine cancers (1); neuroendocrine tumour (1); papillary thyroid cancer (1); pheochromocytoma (1); schizophrenia (1); spina bifida (1).